MMP9 (matrix metallopeptidase 9)
Diseases named in the same sentence as MMP9 in open-access papers (continued):
Sharing a sentence is not in itself a finding about the gene and the disease.
glioblastoma (continued). "The CD133+ glioblastoma cell induced-tumor tissue expressed significantly higher levels of Oct4, Sox2, PCNA, EGFR, Ang2, MMP2 and MMP9 proteins compared with the CD133− glioblastoma cell induced-tumor tissue (P<0.05)." (PMID 23251243, 2013). "It was shown that miR-211 expression was decreased in grade IV glioblastoma multiforme (GBM) and related to the inhibition of invasion and migration of glioma cells through downregulation of MMP-9, and enhancement of apoptosis after temozolomide treatment." (PMID 23965981, 2013). "We found that parthenolide treatment of glioblastoma cells significantly attenuates VEGF and MMP-9 mRNA expression and reduces the secretion of VEGF and MMP-9 protein into the culture medium (*, p < 0.0001)." (PMID 23039130, 2012). "In addition, higher expression levels of MMP9, TERT, VEGFA, ZDHHC18, CHEK2, and ADM elevate the probability of predicting glioblastoma." (PMID 40867242, 2025). "Moreover, activation of the CXCL12/CXCR4 signalling pathway reportedly increases MMP-9 and VEGF expression in glioblastoma." (PMID 38594611, 2024). "Another upregulation compared to the control was detected only in the glioblastoma group for the MMP9 (2.43) and TIMP1 (10.3) genes, both without significance, as well as in meningiomas (TIMP1 = 22.4)." (PMID 38474106, 2024). "Vascular endothelial growth factor (VEGF), matrix metalloproteinase 9 (MMP9), epidermal growth factor receptor (EGFR), and platelet-derived growth factor receptor, genes related to angiogenesis, are overexpressed in glioblastoma and presented on Glioblastoma-EVs surface." (PMID 38379858, 2024). "In conclusion, MMP9 and MUC4 are both expressed in the microvasculature of glioblastoma, indicating both proteins may be involved in angiogenesis and microvascular proliferation (MVP)." (PMID 36400876, 2022). "Moreover, MUC4 is co-expressed with MMP9 and EGFR in the proliferative microvasculature of glioblastoma, suggesting a potential role for MUC4 in microvascular proliferation and angiogenesis." (PMID 36400876, 2022). "MMP9 activity tended to decrease after glioblastoma resection, while no modification was observed after aneurysm resection." (PMID 34980260, 2022). "In intracranial U87 xenografts, immunostaining revealed that bevacizumab-resistant glioblastoma showed an increased amount of TAMs and increased M2/M1 ratio, defined by M2 markers (Arg-1, TGF-β, MMP9) and M1 markers (NOS2, CXCL10, IL-1β), compared to bevacizumab-sensitive glioblastoma." (PMID 34209679, 2021). "In addition, previous reports have also supported the notion that TGF-β-induced MMP-9 expression is mediated through the activation of p38 MAPK, but not ERK1/2, in MCF10A human breast epithelial cells and in human glioblastoma cells." (PMID 34769032, 2021). "Our results suggest that BMAL1 may function as an anti-glioblastoma gene in cell growth, migration, and invasion by regulating Cyclin B, phosphorylated -AKT (p-AKT), and metalloproteinase (MMP)-9 signaling pathways." (PMID 32231148, 2020). "Luteolin in glioblastoma cell lines U251MG and U87MG decreases levels of MMP-2 and MMP-9 protein." (PMID 32102219, 2020). "Taken together, we speculated that HMGN5 in glioblastoma cells could regulate Bcl-2, Bax, Cyclin D1, p21, MMP-2, and MMP-9 to play an oncogenic role partly via the PI3K/AKT pathway." (PMID 32596388, 2020).
glioblastoma (continued). "miR-223 is another well-recognized oncogenic miRNA, which, in glioblastoma, promotes growth and invasion of tumor cells by targeting the tumor suppressor PAX6, exerting its function by inhibiting the expression of metalloproteases MMP2 and MMP9." (PMID 33287106, 2020). "After shikonin treatment on human glioblastoma cells, MMP-2, MMP-9, p-AKT, and p-PI3K decreased." (PMID 29181405, 2017). "To investigate whether GADD45A inhibits expression of β-catenin, MMP-9, and EMT markers, we performed western blotting on total protein extracts from IDH1WT or IDH1R132H glioblastoma cell extracts after GADD45A overexpression." (PMID 28445981, 2017). "In addition, we also identified key genes, including MMP9, CD44, CDC42, COL1A1, COL1A2, CAMK2A, and CAMK2B, as potential target genes for diagnosing glioblastoma." (PMID 28191466, 2017). "Moreover, the inhibition of AEG-1 expression significantly induces the apoptosis and suppresses the invasive ability of human malignant glioblastoma U251 and U87 cells by modulating MMP-2, MMP-9 activity and EMT characteristics." (PMID 27251589, 2016). "Furthermore, both MMP-2 and MMP-9 activities can also be measured in the CSF, and MMP-9 activity in particular was noted to correlate with disease activity in recurrent glioblastoma." (PMID 27876012, 2016). "In human glioblastoma U87 cells, quercetin blocked PMA-induced migration and invasion by inhibiting ERK-dependent COX-2 activation and MMP-9 activity, while in the DAOY medulloblastoma cell line, it reduced both Met-induced cell migration and HGF-mediated Akt activation." (PMID 27827912, 2016). "In addition, biochanin A was reported to inhibit MMP-9 and MT1-MMP in human glioblastoma (U87MG) cells." (PMID 25398247, 2014). "Gelatinase B/MMP-9 inhibitory siRNA inhibits gelatinase B/MMP-9 expression and tumorigenicity in a model of medulloblastoma and miR-491-5p, miR-885-5p and miR-211 inhibit gelatinase B/MMP-9 expression and involvement in models of human glioblastoma." (PMID 24473089, 2014). "Notably, CD133+ glioblastoma cell-induced tumors expressed higher levels of EGFR, Ang2, MMP2 and MMP9 proteins compared with CD133− cell-induced tumors, suggesting that CD133+ cell-induced tumors have a higher degree of malignancy." (PMID 23251243, 2013). "However, recent reports have also indicated that TGF-β-induced MMP-9 expression is mediated through activation of p38 MAPK, but not ERK1/2, in MCF10A human breast epithelial cells and in human glioblastoma cells." (PMID 21134288, 2010). "In oesophageal squamous cell carcinoma (ESCC) and glioblastoma (GBM), SRGN can indirectly upregulate the expression of MMP2/MMP9 by activating the ERK pathway, TGF‐β signalling, or the CXCLs/CXCR2 axis, thereby enhancing tumour invasion and metastasis." (PMID 41410182, 2025). "Patients with glioblastoma and BM showed higher median intra-tumoral MMP-9 levels (8 ng/ml and 4 ng/ml, respectively, p<0.001), increased intra-tumoral MMP-9 activity, and pre-operative serum MMP-9 levels (2.8-fold and 1.8-fold higher than controls, respectively, p<0.001)." (PMID 41573658, 2025). "Moreover, in U87MG glioblastoma cells, treatment with Iso determined an intensification of the proteolytic activity of the metalloproteases after 24 h of treatment; the levels of MMP-2 were reduced with an increase of MMP-9 form." (PMID 36500428, 2022). "We used data from the GEO and TCGA databases and identified five genes (ITGA5, MMP9, PTPRN, PTX3, and STX1A) that could affect the survival rate of glioblastoma patients and that were differentially expressed between glioblastoma patients and non-tumors groups." (PMID 33767729, 2021). "Moreover, MMP-2 and MMP-9, the members of the metalloproteases family, which were frequently involved in glioblastoma invasiveness, were downregulated along with the reduction of HMGN5 in glioblastoma cells." (PMID 32596388, 2020).
glioblastoma (continued). "Thus, COE may inhibit MMP-2 and MMP-9 activity and ECM hydrolysis, thereby attenuating the invasion and migration of glioblastoma cells." (PMID 27716341, 2016). "The US clinical trial “MMP2, MMP9 and NGAL as Biomarkers for Glioblastoma (GBM) Biomarkers for the Prognosis of Glioblastoma (NCT01493219)” has been sponsored by University of Nebraska started since 2011." (PMID 27022952, 2016). "Besides the classical targets VEGF, MMP-9 and PD-1, CHI3L1 constitutes a new possibly drugable molecule to retard down dissemination of SCLC cells, which may be similarly relevant for glioblastoma and other tumor entities." (PMID 26425658, 2015). "Additionally, MMP-9 promotes the proliferation of endothelial cells by releasing vascular endothelial growth factor (VEGF), leading to increased vascular permeability; thus, its pro-angiogenic role in glioblastomas contributes significantly to neovascularization." (PMID 39684754, 2024). "Matrix-metalloproteinase could degrade extracellular matrix proteins to overcome the physical barrier for glioblastoma cells, and studies showed that MMP2 and MMP9 could be regulated by several pathways such as Wnt and PI3K/AKT to promote GBM invasiveness." (PMID 30420967, 2018). "This study aimed to compare the levels of matrix metalloproteinases (MMP2 and MMP9), terminal complement complex (C5b-9), and VEGF-A in circulating sEVs in glioblastoma patients (GBMPs) with and without tumor recurrence." (PMID 39996852, 2025). "Conversely, in glioblastomas with Ki-67 indexes above 20%, the proportion of MMP-9-positive cases decreased to 41.17% (7/17), and MMP-9-negative GBMs were more common (10/17, 58.82%)." (PMID 39684754, 2024). "A clinical trial for recurrent glioblastoma is going to test the combination of monoclonal antibody of MMP-9 combined with bevacizumab (NCT03631836); however, the concept of blocking MMP-9 is related to tumor vascularization but not to its ECM-degrading role." (PMID 31752262, 2019).
myocardial infarction (190 papers, 2005 to 2026). Gross necrosis of the myocardium, as a result of interruption of the blood supply to the area, as in coronary thrombosis. "MMP-9 gene promoter polymorphism has been found in patients with intracranial aneurysm or myocardial infarction." (PMID 37575991, 2023). "In another study using chymase-deficient mice, cardiac MMP-9 activity was markedly reduced compared to that in wild-type mice after myocardial infarction." (PMID 36289761, 2022). "Further, a reduction in macrophage infiltration in infarcted cardiac lesions after myocardial infarction was observed in MMP-9-deficient mice compared with wild-type mice." (PMID 36289761, 2022). "According to our results, the increase in MMP9 is directly associated with plaque instability, greater infarction, impaired left ventricular function, and fatal clinical evolution in acute myocardial infarction with ST elevation." (PMID 34422924, 2021). "An earlier study showed that the high levels of serum HCRP and MMP9 are closely associated with the occurrence of stroke and myocardial infarction in hypertensive patients." (PMID 23606891, 2013). "In our study we observed that the carrier state of allele T of the –1562 C/T MMP9 polymorphism was correlated with hypertension and a higher risk of myocardial infarction." (PMID 23274712, 2013). "Our study indicates that PECAM1 polymorphisms and the –1562 C/T MMP9 polymorphism have a positive effect on (i.e., increase) the risk of myocardial infarction in subjects under 45 years of age." (PMID 23274712, 2013). "High MMP-9 level associated with severity of occluded thrombus and subsequent myocardial infarction." (PMID 28348691, 2012). "Single nucleotide polymorphism (SNP) in the MMP-9 gene promoter, namely the transition of C (cytosine) by T (thymidine) at position -1562, is known to be risk factor for acute myocardial infarction." (PMID 28348691, 2012). "Elevated plasma MMP-9 level during acute myocardial infarction associated with subsequent ventricular remodeling." (PMID 28348691, 2012). "In addition, in patients with myocardial infarction, MMP-9 has been shown to be associated with cardiac remodelling and outcome." (PMID 41503448, 2026). "The most studied MMPs are MMP-2 and MMP-9, whose elevated blood concentrations are strongly associated with heart remodeling disorders, which, for example, can lead to the dilatation of the left ventricle after myocardial infarction." (PMID 39466144, 2025). "This suggests that MMP-9 may be associated with the coronary artery plaque stability and myocardial infarction." (PMID 27375491, 2016). "Vitamin D deficiency has been associated with an increased risk of myocardial infarction (MI), and a significant inverse relationship of 25(OH)D levels and matrix-metalloproteinase-9 (MMP-9), a marker for myocardial remodeling after acute MI, has been documented." (PMID 23912328, 2013). "In addition to HCRP, MMP9 is another risk factor correlated to atherosclerosis, myocardial infarction, and ischemic stroke." (PMID 23606891, 2013). "Furthermore, this study also suggested relation between MMP polymorphism with increased serum MMP-9 levels in acute myocardial infarction." (PMID 28348691, 2012). "Current findings on the association between MMP-9 rs3918242 and susceptibility to myocardial infarction (MI) are inconsistent, and their definite relationship is discussed in this meta-analysis." (PMID 35075377, 2022). "Among them, elevated MMP-9 concentration has been a risk factor for future myocardial infarction or coronary revascularization and heart failure by myocardial remodeling after acute myocardial infarction, in addition to acute lung injury and chronic obstructive pulmonary disease." (PMID 26273135, 2015).
myocardial infarction (continued). "Moreover, gelatinases A and B (MMP-2 and MMP-9) constitute risk factors for myocardial infarction whereas their tissue inhibitors TIMPs have an impact on postmyocardial infarction remodelling and correlate positively with left ventricular mass and wall thickness." (PMID 22383985, 2012). "Therefore, the inhibitory effect of rosiglitazone on MMP-9 found in the present study may contribute to beneficial effects of rosiglitazone on cardiovascular risk of the patients with previous acute myocardial infarction." (PMID 22716287, 2012). "Regarding cardiovascular pathology, MMP-2 and MMP-9, also known as gelatinase A and B, act as key contributors to the development of atherosclerosis, myocardial infarction (MI), HF, and coronary thrombosis." (PMID 40305314, 2025). "Multiple studies have confirmed that MMP9 induces tissue damage via the NETs pathway in diseases such as osteoarthritis and myocardial infarction." (PMID 40620701, 2025). "Studies on MMPs have shown that early inhibition of MMP-9 activity after acute myocardial infarction helps resolve inflammation." (PMID 40468054, 2025). "Another study where treatment with ONO-4817 significantly inhibited MMP-9 activity demonstrated attenuated left ventricular remodeling within one day after myocardial infarction, highlighting its potential therapeutic role in post-MI complications." (PMID 40305314, 2025). "A 2014 study reported the development of activatable cell-penetrating probes designed to assess MMP-2 and MMP-9 activity, though in the distinct context of post-myocardial infarction cardiac remodeling in murine models." (PMID 41206839, 2025). "The level of MMP-9 is directly correlated with the activity of fibrinogen, C-reactive protein, and IL-6, which are markers for predicting the risk of myocardial infarction (MI)." (PMID 39335497, 2024). "In this research, the content of collagen and the expression of matrix metalloproteinase-9 (MMP-9) in p50 knockout mice were significantly lower after myocardial infarction." (PMID 39717608, 2024). "It inhibits the activation of the NLRP3 inflammasome, exhibiting antidepressant and neuroprotective effects, and significantly reduces MMP-9 expression in myocardial infarction models." (PMID 39295943, 2024). "In this study involving Chinese patients with myocardial infarction and a coronary arteriosclerosis group, elevated levels of both circulating MMP-9 and TIMP-1 were observed." (PMID 39195176, 2024). "The levels of MMP9 are markedly increased in post-myocardial infarction patients, and high MMP9 is an independent predictor of 2-year adverse cardiovascular events." (PMID 37469874, 2023). "Carvedilol has also been reduced the levels of MMP-2 and MMP-9 an animal model of acute myocardial infarction." (PMID 37122872, 2023). "After myocardial infarction in hamsters, lisinoprilsignificantly inhibited activities of both angiotensin converting enzyme and MMP-9." (PMID 37886137, 2023). "As MMP9 is secreted by neutrophils, it follows that high levels of this protease is present in myocardial infarction and participates in the process of post-infarct remodeling, impeding tissue repair and angiogenesis." (PMID 37512106, 2023). "MPO and MMP-9 are related to such processes as inflammation, tissue damage, and tissue remodelling in individuals with myocardial infarction." (PMID 37569455, 2023). "Lisinopril, anangiotensin converting enzyme inhibitor, significantly inhibited MMP-9 activity after myocardial infarction in hamsters." (PMID 37886137, 2023). "MMP-9 expression was also tested in a prospective cohort study with 91 acute myocardial infarction patients at intervals (0–12, 12–24, 24–48, 48–72, 72–96, and > 96 h)." (PMID 35410418, 2022). "In contrast, cardiac dysfunction after myocardial infarction was significantly attenuated by an MMP-9 inhibitor or a chymase inhibitor." (PMID 36289761, 2022).